PDLIM1 (PDZ and LIM domain 1)
Description:
Cytoskeletal protein that may act as an adapter that brings other proteins (like kinases) to the cytoskeleton. Involved in assembly, disassembly and directioning of stress fibers in fibroblasts. Required for the localization of ACTN1 and PALLD to stress fibers. Required for cell migration and in maintaining cell polarity of fibroblasts (By similarity).
Synonyms: CLIM1; CLP36; CLP-36; hCLIM1; HEL-S-112
Tractability: PROTAC: ubiquitination databases record sites on it; its protein half-life has been measured.
Gene: Protein-coding gene on chromosome 10 (95,237,569 to 95,291,035, reverse strand). Ensembl gene ENSG00000107438.
Subcellular location: Cytoplasm; Cytoplasm, cytoskeleton; Cytoplasm, myofibril, sarcomere, Z line
Subcellular location (Human Protein Atlas): Actin filaments; Cell Junctions; Plasma membrane
Gene Ontology:
Molecular function: cadherin binding involved in cell-cell adhesion; protein binding; actin binding; muscle alpha-actinin binding; transcription coactivator activity
Biological process: actin cytoskeleton organization; establishment or maintenance of actin cytoskeleton polarity; fibroblast migration; heart development; maintenance of cell polarity; muscle structure development; response to oxidative stress; stress fiber assembly; cell-cell adhesion; positive regulation of DNA-templated transcription; response to hypoxia
Cellular component: actin cytoskeleton; adherens junction; cytoplasm; cytoskeleton; focal adhesion; stress fiber; Z disc; filamentous actin; transcription regulator complex
Genetic constraint (gnomAD): Loss-of-function variants: 19 observed, 26 expected, observed/expected ratio (o/e) 0.73, 90% interval 0.51 to 1.07. The upper end of that interval is the gene's LOEUF score, 1.07, which puts it in group 4 of 6, group 1 being the genes least tolerant of losing a copy. Missense variants: 318 observed, 365.84 expected, observed/expected ratio (o/e) 0.87, 90% interval 0.79 to 0.95. Synonymous variants: 134 observed, 141.29 expected, observed/expected ratio (o/e) 0.95, 90% interval 0.82 to 1.1.
Homologues: Orthologues: chimpanzee PDLIM1 (99% identical), macaque PDLIM1 (99% identical), dog PDLIM1 (94% identical), pig PDLIM1 (94% identical), rabbit PDLIM1 (92% identical), guinea pig PDLIM1 (91% identical), mouse Pdlim1 (89% identical), rat Pdlim1 (89% identical), zebrafish pdlim1 (70% identical), tropical clawed frog pdlim1 (63% identical), Caenorhabditis elegans alp-1 (27% identical), Drosophila melanogaster Zasp52 (23% identical). Paralogues in human: PDLIM3 (46% identical), PDLIM4 (45% identical), LDB3 (36% identical), PDLIM2 (35% identical), PDLIM5 (31% identical), PDLIM7 (29% identical), PRICKLE4 (14% identical).
Diseases named in the same sentence as PDLIM1 in open-access papers:
PDLIM1 is named in the same sentence as 63 diseases in open-access papers, as found by Europe PMC text mining. Sharing a sentence is not in itself a finding about the gene and the disease. The quoted sentences say what the papers report.
breast carcinoma (11 papers, 2016 to 2025). "In a few studies on autoantibody against PDLIM1, PDLIM1 was identified as a tumor-associated antigen (TAA) due to inducement of autoantibody response in patients with breast cancer and pancreatic cancer." (PMID 34489945, 2021). "Studies indicated that the abnormal expression of PDLIM1 is associated with hepatocellular carcinoma, breast cancer, colorectal cancer, and pancreatic cancer." (PMID 34489945, 2021). "Pdlim1 is expressed in fibroblasts and involved in cell polarity and migration and has been shown to be associated with breast cancer progression." (PMID 35087569, 2021). "Dysregulation of PDLIM1 has been observed in multiple cancers, including colorectal cancer, hepatocellular carcinoma, breast cancer, and glioma." (PMID 39548074, 2024). "In breast cancer, PDLIM1 binds to α-actinin-4, activating CDC42 and promoting cell invasion and metastasis." (PMID 39548074, 2024). "For example, PDLIM1 promotes metastasis in glioblastoma and breast cancer, however, PDLIM1 inhibits metastasis in CRC10,13,15." (PMID 37414929, 2023). "It serves as an important regulator for breast cancer cell migration and metastasis, and the increased expression of PDLIM1 contributes to the progression of breast cancer." (PMID 34489945, 2021). "In Liu’s study, PDLIM1 was reported to promote breast cancer cell migration and invasion in vitro and metastasis in vivo through interaction with α-actinin." (PMID 34489945, 2021). "Disruption of this interaction by deleting the PDZ domain eliminates PDLIM1-mediated cell migration, further demonstrating the essential role of PDLIM1-α-actinin complex in breast cancer migration and invasion." (PMID 34396044, 2021). "Another study also reported that anti-PDLIM1 AAb identified breast cancer from controls with a sensitivity of 73.4% and specificity of 58.3%." (PMID 34489945, 2021). "However, in breast cancer mouse models, PDLIM1 expression seems to increase during cancer progression." (PMID 40278994, 2025). "Notably, the PDZ domain is responsible for the binding of PDLIM1 to α-actinin in breast cancer cells." (PMID 34396044, 2021). "Importantly, PDLIM1 combines with α-actinin-4 to form a PDLIM1-α-actinin complex, thereby promoting the activation of Cdc42, which is a key factor in regulating cell polarity and migration of breast cancer cells." (PMID 34396044, 2021). "The top five hub genes for the hormone-like community were KRT18, JUP, KRT8, SH2D3A and PDLIM1; KRT18 and KRT8 are luminal markers in breast cancer while JUP (plakoglobin), SH2D3A and PDLIM1 are relatively undescribed in the context of cancer." (PMID 39556603, 2024). "However, increasing evidence recently demonstrates that PDLIM1 is dysregulated in a variety of tumors, such as colorectal cancer (CRC), hepatocellular carcinoma (HCC), breast cancer, pancreatic cancer, glioma and chronic myelogenous leukaemia (CML)." (PMID 34396044, 2021). "Secondly, anti-PDLIM1 AAb is not fully specific to OC; it was also detected in breast cancer and pancreatic cancer." (PMID 34489945, 2021).
colorectal cancer (10 papers, 2020 to 2025). A primary or metastatic malignant neoplasm that affects the colon or rectum. "Furthermore, in vivo experiments using mouse models showed that loss of PDLIM1 promotes invasiveness and metastasis in colorectal cancer, while overexpression inhibited the process." (PMID 40278994, 2025). "Expression of PDLIM1 was significantly lower in colorectal cancer tissue samples compared with adjacent normal mucosal tissues." (PMID 40278994, 2025). "For example, in colorectal cancer, PDLIM1 facilitates the binding of β-catenin to E-cadherin, sequestering β-catenin in the cytoplasm, thereby inhibiting the Wnt/β-catenin pathway and suppressing tumor progression." (PMID 39548074, 2024). "According to previous reports, PDLIM1 has a regulatory effect on the Wnt/β-catenin pathway in colorectal cancer and chronic myeloid leukemia, whereas its detailed function in DR has not been reported." (PMID 37037887, 2023). "PDLIM1 has been shown to regulate β-catenin in the classic Wnt pathway in colorectal cancer and promote the migration of cancer cells in chronic myeloid leukemia through the Wnt/β-catenin pathway." (PMID 37037887, 2023). "For instance, PDLIM1 stabilizes β-catenin at the cell-to-cell junction to suppress epithelial mesenchymal transformation and metastatic potential in colorectal cancer." (PMID 36164345, 2022). "PDLIM1 is upregulated in neoHFFs activated by late-stage colorectal cancer-exosomes (exosomes derived from SW620 CRC cells), allowing cells to acquire the ability to invade through the extracellular matrix." (PMID 34396044, 2021). "The study of CAMs showed that PDLIM1 inhibits colorectal cancer cell metastasis by stabilizing the E-cadherin/beta-catenin complex." (PMID 32371982, 2020). "In colorectal cancer, PDLIM1 could inhibit EMT and the metastatic potential of colorectal cancer cells via stabilizing the E-cadherin/β-catenin complex." (PMID 36901953, 2023). "The degradation of PDLIM1 directly promotes the invasion and metastasis of colorectal cancer cells." (PMID 32371982, 2020). "PDLIM1, a scaffold protein, exerts inhibition on the epithelial-mesenchymal transition (EMT) and migration potential of colorectal cancer cells by stabilizing β-catenin at cell-cell junctions." (PMID 39148969, 2024).
glioma (10 papers, 2018 to 2024). A benign or malignant brain and spinal cord tumor that arises from glial cells (astrocytes, oligodendrocytes, ependymal cells). "PDZ and LIM domain 1 (PDLIM1) might be associated with glioma invasion and was highly expressed in multicentric GBM, suggesting its potential role in promoting GBM aggressiveness." (PMID 37700319, 2023). "In glioma, PDLIM1 was previously demonstrated to act as an adapter to p75NTR, driving glioma invasion." (PMID 39548074, 2024). "In glioma, PDLIM1 has been identified as an adapter to the neurotrophin receptor p75NTR, mediating glioma invasion." (PMID 39548074, 2024). "Overall, the interaction of p75NTR and PDLIM1, which depends on the unphosphorylated state of S425, mediates the invasion of glioma." (PMID 34396044, 2021). "p75 neurotrophin receptor (p75NTR/CD271) mediates glioma invasion that requires regulated interaction with PDLIM1." (PMID 32938376, 2020). "Moreover, knockdown of PDLIM1 by shRNA abolished p75NTR-mediated glioma invasion in vitro and in vivo." (PMID 34396044, 2021). "Consequently, disruption of the interaction between the PDZ domain of PDLIM1 and p75NTR may provide potential therapeutic strategies for patients with glioma." (PMID 34396044, 2021).
hepatocellular carcinoma (10 papers, 2020 to 2025). A malignant tumor that arises from hepatocytes. "Similarly, elevated expression of PDLIM1 was associated with a reduced invasive ability of colorectal and hepatocellular cancer cells, which coincides with the mesenchymal phenotype of therapy-induced persistence." (PMID 33330109, 2020). "In hepatocellular carcinoma, PDLIM1 competitively binds to ACTN4, disrupting the interaction between ACTN4 and F-actin, thereby activating the Hippo pathway and inhibiting metastasis." (PMID 39548074, 2024). "During metastasis of hepatocellular carcinoma (HCC), PDLIM1 was demonstrated to play an important inhibitory role through activating the Hippo signaling pathway." (PMID 34489945, 2021). "Low PDLIM1 expression correlates with metastasis and poor prognosis in liver cancer, where it limits F–actin formation and reverses EMT, suppressing hepatocellular carcinoma metastasis." (PMID 40243891, 2025). "Previous research has also reported that PDLIM1 can inhibit YAP, thereby suppressing hepatocellular carcinoma metastasis." (PMID 40243891, 2025). "Huang’s study showed that PDLIM1 is significantly downregulated in the tissues of metastatic hepatocellular carcinoma (HCC), suggesting that PDLIM1 may be a potential prognostic marker for metastatic hepatocellular carcinoma." (PMID 34489945, 2021). "However, in hepatocellular carcinoma (HCC), PDLIM1 was poorly expressed, and overexpression of PDLIM1 in HCC competed for binding with the ACTN4, resulting in the dissociation of ACTN4 from F-actin." (PMID 37894409, 2023).
chronic myeloid leukemia (7 papers, 2021 to 2024). "PDLIM1 is regulated by miR-370-3p and influences the proliferation and apoptosis of chronic myelogenous leukemia (CML) cells through the Wnt/β-catenin pathway." (PMID 39548074, 2024). "In chronic myeloid leukemia, PDLIM1 has been reported as a target to promote the migration of cancer cells via the Wnt/β-catenin pathway." (PMID 37037887, 2023). "Moreover, PDLIM1 promotes proliferation and impedes apoptosis to play a carcinogenic part in chronic myeloid leukemia (CML)." (PMID 36164345, 2022). "In addition, a study indicated that PDLIM1 could promote proliferation and suppress apoptosis of chronic myeloid leukemia cells, having an oncogenic role to chronic myeloid leukemia." (PMID 34489945, 2021). "While trying to link CLP36/PDLIM1 with malignancies, it should be noticed that CLP36 is involved in the apoptosis and proliferation of chronic myelogenous leukemia cells (Li, Luo & Song, 2020)." (PMID 39735560, 2024).
gastric cancer (6 papers, 2022 to 2025). A primary or metastatic malignant neoplasm involving the stomach. "In gastric cancer cells, PDLIM1 (PDZ and LIM domain protein 1) interacted with HK2 (Hexokinase 2) to drive glycolysis, proliferation, migration, and apoptosis resistance via Wnt/β-catenin signaling, particularly under glucose-deprived conditions." (PMID 40917745, 2025). "The cell models of PDLIM1 overexpression and low expression were established in gastric cancer cell lines MKN45 and AGS." (PMID 36164345, 2022). "The function and mechanism of PDLIM1, a cancer-suppressing gene, in gastric cancer progression remain unclear." (PMID 36164345, 2022). "Intriguingly, the overexpression of PDLIM1 has also been shown to attenuate the cancer-promoting function of miR-187 in gastric cancer (GC) cells and increase their sensitivity to cisplatin." (PMID 38739940, 2024). "Additionally, PDLIM1 modulates the Warburg effect—a phenomenon where cancer cells exhibit increased glucose uptake and lactate production, critical for the tumor microenvironment—by interacting with HK2 and regulating the Wnt/β-catenin pathway in gastric cancer." (PMID 39548074, 2024).
ovarian carcinoma (4 papers, 2021 to 2024). A malignant neoplasm originating from the surface ovarian epithelium. "This study aims to evaluate the diagnostic value of autoantibody against PDLIM1 for improving the detection of ovarian cancer (OC)." (PMID 34489945, 2021). "In the current study, we aim to explore the occurrence and presentation level of anti-PDLIM1 autoantibodies in the sera of patients with ovarian cancer and further to evaluate its potential as a biomarker for the detection of OC." (PMID 34489945, 2021). "Consequently, anti-PDLIM1 AAb has great potential as a serological marker of ovarian cancer." (PMID 34489945, 2021). "In addition, PDLIM1 RNA levels were significantly higher in pancreatic cancer cell lines compared to colon, lung, and ovarian cancer cell lines, and PDLIM1 was located in both cell membrane and cytoplasm, suggesting that PDLIM1 may be a tumor autoantigen in pancreatic cancer." (PMID 34396044, 2021). "Anti-PDZ and LIM domain-1 (PDLIM1) AAbs were able to differentiate both ovarian cancer patients from healthy controls (AUC 0.76) and ovarian benign tumors (AUC 0.76), as well as to identify 41% of early-stage and 39% of late-stage ovarian cancer, respectively." (PMID 38275400, 2024). "The anti-PDLIM1 AAbs could also find 15% of ovarian cancer patients negative on the base of CA125 marking alone." (PMID 38275400, 2024). "No reports have been found about the expression of PDLIM1 in ovarian cancer tissues and whether there is an autoantibody response to PDLIM1 in patients with ovarian cancer." (PMID 34489945, 2021).
lymphoma (3 papers, 2022 to 2024). A malignant (clonal) proliferation of B- lymphocytes or T- lymphocytes which involves the lymph nodes, bone marrow and/or extranodal sites. "Relevant data have suggested that CLP36 (shown as PDLIM1 in the figures) was highly expressed in lymphoma (P < 0.05), and such high CLP36 expression in lymphoma was related to an unfavorable overall survival of lymphoma patients (logrank P = 0.02)." (PMID 39735560, 2024). "CLP36 is also known as PDZ and LIM Domain 1 (PDLIM1) that is a ubiquitously-expressed α-actinin-binding cytoskeletal protein involved in carcinogenesis, and our current study aims to explore its involvement in lymphoma." (PMID 39735560, 2024). "Further investigations are warranted to elucidate the precise expression patterns and functional roles of PDLIM1 in DLBCL, which could potentially lead to novel therapeutic strategies for this aggressive lymphoma." (PMID 39564935, 2024).
osteosarcoma (3 papers, 2009 to 2022). A usually aggressive malignant bone-forming mesenchymal neoplasm, predominantly affecting adolescents and young adults. "For example, overexpression of Pdlim4 in osteosarcoma cells causes continuous assembly and collapse of stress fibers, resulting in rapid changes in cell shape, while knockdown of Pdlim1 in BeWo cells leads to loss of stress fibers and focal adhesions." (PMID 27792740, 2016).
atherosclerosis (2 papers, 2022 to 2025). A disease characterized by the build-up of fatty material and calcium deposition in the arterial wall resulting in partial or complete occlusion of the arterial lumen. "We identified 12 lactylation-related genes that are more reliably associated with atherosclerosis: five upregulated genes (LSP1, IKZF1, MNDA, RCC2, and WAS) and seven downregulated genes (CSRP2, PPP1CB, CSRP1, HEXIM1, CALD1, PDLIM1, and RANBP2)." (PMID 40248193, 2025). "The related genes such as TOMM5, and MYLK have been reported to have implications in diabetes, and PDLIM1 and CAMK2G were found to be related to atherosclerosis." (PMID 35508613, 2022).
diabetes (2 papers, 2022 to 2023). "Functional analysis and lncRNA-mRNA network analysis showed that it contained many genes that have been reported to be related to diabetes and vascular diseases, such as TOMM5, MYLK, PDLIM1, and CAMK2G." (PMID 35508613, 2022).
diabetic retinopathy (2 papers, 2023 to 2024). "Similarly, PDLIM1 directly regulates Wnt3a expression, influencing cell migration and invasion in diabetic retinopathy." (PMID 39548074, 2024).
fibrosis (2 papers, 2016 to 2023). the formation of excess fibrous connective tissue in an organ or tissue in a reparative or reactive process. "Tissue IF showed that PDLIM1 co-localized with α-SMA in liver tissue of fibrosis mice." (PMID 37414929, 2023).
liver fibrosis (2 papers, 2023 to 2024). "Next, we showed that the expression of PDLIM1 was markedly upregulated in liver fibrosis models by IHC." (PMID 37414929, 2023). "To investigate the role of PDLIM1 in the development of liver fibrosis, we first induced liver fibrosis in mice by CCl4 treatment for 6 weeks." (PMID 37414929, 2023). "In this study, PDLIM1 was upregulated in CCl4-induced liver fibrosis mouse models and TGF-β-treated HSC-T6 cells." (PMID 37414929, 2023). "Next, to clarify the role of PDLIM1 in liver fibrosis progression, we conducted an RNAi experiment using specific siRNA to knockdown PDLIM1 expression." (PMID 37414929, 2023). "Therefore, in this study, we first investigated the expression of PDLIM1 in mouse models of liver fibrosis and HSC-T6 cells." (PMID 37414929, 2023). "Taken together, these results suggest that PDLIM1 expression is increased in liver fibrosis models." (PMID 37414929, 2023). "In our current research, we found that PDLIM1 might be a pro-fibrotic factor in the initiation of liver fibrosis, and the dynamic expression of PDLIM1 correlated with its different roles at different stages of liver disease." (PMID 37414929, 2023). "Our results suggest that PDLIM1 can accelerate the activation of HSCs and liver fibrosis progression and could be a potential biomarker for monitoring response to anti-fibrotic therapy." (PMID 37414929, 2023). "However, the potential functions and mechanism of PDLIM1 in HSCs activation and liver fibrosis progression remains enigmatic." (PMID 37414929, 2023). "Collectively, our findings suggest that PDLIM1 may serve as a promising biomarker and therapeutic target for liver fibrosis." (PMID 37414929, 2023). "Therefore, the role of CTCF in the process of liver fibrosis and how CTCF helps PDLIM1 promote liver fibrosis is worth exploring." (PMID 37414929, 2023). "Our results suggest that PDLIM1 can accelerate the activation of HSCs and liver fibrosis and could be a potential biomarker for liver fibrosis." (PMID 37414929, 2023). "However, whether and how CTCF plays a role in liver fibrosis and the relationship between PDLIM1 and CTCF during HSCs activation remains unclear." (PMID 37414929, 2023). "However, the regulatory mechanism of PDLIM1 in liver fibrosis still needs more in-depth study." (PMID 37414929, 2023).